CX3CR1 (C-X3-C motif chemokine receptor 1)
Diseases named in the same sentence as CX3CR1 in open-access papers (continued):
Sharing a sentence is not in itself a finding about the gene and the disease.
atherosclerosis (continued). "Previous studies have revealed that the CX3CL1/CX3CR1 axis is responsible for numerous pathological processes, such as atherosclerosis, atherogenesis, nervous system diseases, vasculitis, abnormal heart function, and cancer development." (PMID 35140706, 2021). "The current study provides evidence of the correlation between shear stress and atherosclerosis mediated by CX3CR1." (PMID 32686027, 2020). "TEM and TEMRA cells remain CCR7- and maintain both memory and flexibility of cytokine gene expression, but they also upregulate CX3CR1 which allows them to bind to vascular endothelium and promote atherosclerosis." (PMID 32249825, 2020). "Of the specific top‐listed differentially expressed genes, two upregulated genes, CX3CR1 and ARID5B, have been previously associated with atherosclerosis." (PMID 32107839, 2020). "While CX3CL1 and CX3CR1 are expressed at low levels in healthy vessels, their expression increases significantly under pathological conditions, and pharmacological inhibition of CX3CR1 (the CX3CR1 antagonist F1) has been reported to reduce atherosclerosis." (PMID 32686027, 2020). "The current data provide evidence of the correlation between shear stress and atherosclerosis that is regulated by CX3CR1." (PMID 32686027, 2020). "Atherosclerosis is ameliorated in ApoE-/- mice in which the CX3CL1/CX3CR1 pathway has been genetically deleted or pharmacologically blocked." (PMID 29641559, 2018). "Studies disrupting the chemokine pathway CX3CL1 (fractalkine)/ CX3CR1 have shown decreased atherosclerosis in animal models but the techniques used to interrupt the pathway have not been easily translatable into human trials." (PMID 29641559, 2018). "CCL2/CCR2 and CX3CL1/CX3CR1 contribute significantly to the recruitment and stimulation of monocytes/macrophages during the pathogenesis of atherosclerosis, and are expressed in early and advanced atherosclerotic lesions in humans and mice." (PMID 29641559, 2018). "We evaluated the effect of a DNA vaccine, targeted to CX3CR1, on atherosclerosis in a murine model and examined possible mechanisms of action." (PMID 29641559, 2018). "The primary mode of action of CX3CL1/CX3CR1 in atherosclerosis seems to be recruitment of monocytes and accordingly in this model there was a marked reduction in the macrophage content of the plaques." (PMID 29641559, 2018). "Pharmacological inhibition of the chemokine receptor, CX3CR1 has furthermore been described to inhibit leukocyte recruitment and to reduce atherosclerosis, indicating an important role of CX3CL1 in the pathogenesis of atherosclerosis." (PMID 28234900, 2017). "H2S has been reported to hamper the progression of atherosclerosis in fat-fed ApoE−/− mice and down-regulate CX3CR1 and CX3CL1 expression by modulating PPARγ in macrophages and lesion plaques." (PMID 27136542, 2016). "Inhibition of the CX3CL1/CX3CR1 signaling pathway ameliorated the severity of atherosclerosis in animal models." (PMID 25959742, 2015). "Both CX3CL1-/- and CX3CR1-/- knockout mice crossed into the apoE-/- model of atherosclerosis showed a significant reduction in macrophage recruitment to the vessel wall and decreased atherosclerotic lesion formation compared to normal animals." (PMID 24995121, 2014). "In conclusion, these data indicate that H2S hampers the progression of atherosclerosis in fat-fed apoE−/− mice and downregulates CX3CR1 and CX3CL1 expression on macrophages and in lesion plaques." (PMID 22815945, 2012). "Recent studies have shown that PPARγ has the inherent capacity to regulate expression of macrophage chemokine receptors CX3CR1 in the lipid-mediated inflammation process of atherosclerosis lesions." (PMID 22815945, 2012). "In contrast, inhibition of endogenous H2S formation upregulated aortic expression of CX3CL1 and CX3CR1, thus exacerbating atherosclerosis in aorta." (PMID 22815945, 2012).
atherosclerosis (continued). "The significance of chemokines (CCL2 [monocyte chemotactic protein-1], CCL5 [RANTES] and CX3CL1 [fractalkine]) and their receptors (CCR2, CCR5 and CX3CR1) in atherosclerosis has been demonstrated in animal models and clinical studies." (PMID 22815945, 2012). "Experiments that followed atherosclerotic lesion development over several days suggested that CX3CR1 represents an important receptor for monocytes to accumulate in plaque in murine models of atherosclerosis." (PMID 22916279, 2012). "The FKN/CX3CR1 axis has been involved in the pathogenesis of numerous disorders including atherosclerosis, vasculitis, renal disease and kidney allograft rejection." (PMID 22039526, 2011). "Combined inhibition of CCL2, CCR5 and CX3CR1 in ApoE-/- mice results in a 90% reduction in atherosclerosis, which is related to progressive monocytopaenia." (PMID 21526997, 2011). "The function of CX3CR1 in atherosclerosis was further confirmed by studies showing that inactivating the CX3CR1 gene reduced the atherosclerotic lesion area as compared with wild mice in the apoe−/− background." (PMID 19587779, 2009). "A bioinformatic analysis and machine learning algorithms approach illustrated that 5 hub genes (SPI1, MMP9, C1QA, CX3CR1, MNDA) could predict the risk of atherosclerosis in SLE." (PMID 40725777, 2025). "Targeting CX3CR1-expressing monocytes may help mitigate atherosclerosis, as chronic inflammation from these cells likely exacerbates dyslipidemia and increases cardiovascular risk." (PMID 40620597, 2025). "In addition, it has been found that CX3CR1/NF-κB is involved in atherosclerosis and promotes monocyte adhesion and cell migration." (PMID 40727388, 2025). "CX3CR1 and ST6GAL1 genes have been identified in association with atherosclerosis." (PMID 41141090, 2025). "Chemokines, including CX3CR1, could regulate atherosclerosis through mediating the targeting of Stabilin factor by immune cells, such as monocytes and macrophages." (PMID 40727388, 2025). "CX3CR1 is a chemokine and a typical regulator of atherosclerosis development." (PMID 40727388, 2025). "Cytotoxic CD4+ T cells express markers which have been implicated in atherosclerosis in PLWH, including CD57 (a marker of senescence), CX3CR1 (a chemokine receptor that homes cells to inflamed endothelium), and GPR56 (an adhesion g-coupled protein receptor that is expressed on exhausted T cells)." (PMID 39000373, 2024). "Solid literature evidence supports the contribution of specific monocyte subsets to the process of atherosclerosis, with studies in mice demonstrating the recruitment of non-classical monocytes into the plaque via the chemokine receptor CX3CR1 and its ligand CX3CL1/FKN." (PMID 38247848, 2024). "Besides, flavonoids reduced the atherosclerosis plaque size by diverse mechanisms, such as the ROS/JNK pathway and the CX3CR1 signaling, leading to anti-atherosclerosis effects." (PMID 38026172, 2023). "Although Cx3cr1 has been shown to be important for the recruitment of monocytes to several inflammatory tissues, including myocardial infarction and atherosclerosis, two previous studies also showed that Cx3cr1 is dispensable for the recruitment of Ly6Clo macrophages to injured muscle tissues." (PMID 38259495, 2023). "In addition, in atherosclerosis, many studies have shown that CX3CL1/CX3CR1 signaling was implicated in angiogenesis during plaque microvessel formation." (PMID 37248293, 2023). "Blocking the CX3CL1/CX3CR1 pathway in in vivo studies ameliorated the severity of atherosclerosis." (PMID 35350534, 2022). "The role of CX3CR1 in angiogenic T cell function is not well defined, in animal models, CX3CR1 expression is associated with enhanced atherosclerosis and renal impairment suggesting a pro-inflammatory potential of these cells." (PMID 34079548, 2021).
atherosclerosis (continued). "Furthermore, literature searches revealed various other studies that focused on the amelioration of atherosclerosis and related disorders by disrupting chemokine signaling, which focused for example on CX3CR1, MIF, CXCR3, and the CCL5-CXCL4 heterodimer." (PMID 34501271, 2021). "Instead, the authors observed that CX3CR1 deficiency resulted in reduced T helper 17 (TH17) cell polarization within atherosclerotic plaques and that this was necessary for the development of CKD-driven atherosclerosis." (PMID 34163473, 2021). "Interestingly, TNF-alpha and CX3CR1 expression positively correlated with increased intima-media thickness and hs-CRP, both of which are markers of atherosclerosis and cardiovascular risk." (PMID 34439835, 2021). "In addition, the CX3CL1/CX3CR1 axis is a central player in inflammatory disorders such as atherosclerosis development." (PMID 34504250, 2021). "Additionally, we found elevated gene expression associated with cell motility, including the CX3CR1 and ARID5B genes, which have been associated with the development of atherosclerosis." (PMID 32107839, 2020). "In a cohort of virologically suppressed HIV-positive individuals with low cardiovascular risk, we have previously demonstrated an association between the proportion of CX3CR1+ CD16+ monocytes and cIMT, supporting a potential link between monocyte recruitment and atherosclerosis." (PMID 31275317, 2019). "To assess the effect of blocking the CX3CL1/CX3CR1 pathway on atherogenesis we developed a DC-targeted DNA vaccination against CX3CR1 that was used in a murine model of atherosclerosis,feeding the mice a normal chow diet to more closely mimic the atherosclerotic lesions found in humans." (PMID 29641559, 2018). "Small molecules against CX3CR1 can prevent atherosclerosis in mice." (PMID 28522896, 2017). "Animal models suggest that the fractalkine/CX3CR1 pathway is involved in the recruitment of EPCs to the ischaemic sites during stroke and regulates progenitor-dependent endothelial repair during atherosclerosis." (PMID 28320472, 2017). "More recently the importance of CX3CL1 and its receptor (CX3CR1) in atherosclerosis has emerged." (PMID 28282403, 2017). "In 2003 a CX3CR1 knockout mouse displayed reduced atherosclerosis." (PMID 26656484, 2016). "Indeed, Cx3cr1 has been found to promote atherosclerosis lesion by regulating macrophage accumulation, and blockade of Cx3cr1 attenuates renal pro-inflammatory responses and fibrosis after ischemia-reperfusion insult." (PMID 26035381, 2015). "In humans, CX3CR1 polymorphisms in the coding region of the gene are a genetic risk factor for early onset coronary artery disease, strongly supporting a mechanistic role for CX3CL1 in the pathogenesis of atherosclerosis." (PMID 24995121, 2014). "CX3CR1 is required for monocyte survival and differentiation in atherosclerosis and liver fibrosis." (PMID 24245985, 2013). "The chemokine receptors CCR2 and CX3CR1 are critical for the recruitment of “inflammatory” and “resident” monocytes, respectively, subpopulations that differentially affect vascular remodeling in atherosclerosis." (PMID 23029475, 2012). "Therefore, the present study aimed to investigate the potential role of H2S in atherosclerosis and the underlying mechanism with respect to chemokines (CCL2, CCL5 and CX3CL1) and chemokine receptors (CCR2, CCR5, and CX3CR1) in macrophages." (PMID 22815945, 2012). "H2S may prevent the progression of atherosclerosis, along with downregulating macrophage CX3CR1 and CX3CL1 expression by a PPAR-γ and NF-κB dependent mechanism." (PMID 22815945, 2012). "Interestingly, concurrent studies have provided functional evidences that CX3CR1 and its ligand serve as important mediators of inflammation and pathology in animal models models for atherosclerosis, transplant rejections, glomerulonephritis and stroke." (PMID 16053521, 2005).
atherosclerosis (continued). "Therefore, IR and the CX3CL1/CX3CR1 axis could be two important mechanisms driving accelerated atherosclerosis in these subjects." (PMID 41153665, 2025). "While its exact role in the development of atherosclerosis is not fully understood, it can be hypothesized that its low levels in BD patients encourage a prolonged inflammatory state, thereby promoting plaque development in a similar manner to the CX3CR1 gene." (PMID 41141090, 2025). "Furthermore, CX3CR1 is known to be involved in atherosclerosis and vascular inflammation." (PMID 35625386, 2022). "In addition, CX3CR1 plays a role in the formation of atherosclerosis." (PMID 32686027, 2020). "We hypothesize that migration of CX3CR1+ CD8 T cells into plaque could contribute to endothelial damage in atherosclerosis through direct targeting of activated endothelium and/or indirect cytokine-mediated activity, possibly by activating other infiltrating inflammatory cells." (PMID 32976527, 2020). "Thus, we have identified a possible feed-forward model of atherosclerosis in which plaque-infiltrating CX3CR1+ CD8 T cells are exposed to vascular EC-derived IL-15 that induces antigen-independent TNF release, resulting in enhanced release of CX3CL1 and IL-15 from ECs." (PMID 32976527, 2020). "Indeed, F4/80+ macrophages express various chemokine receptors including CX3CR1, and genetic disruption or immunoneutralization of CX3CR1 impaired macrophage recruitment in atherosclerosis, wound healing, and renal diseases, thereby preventing or alleviating pathological changes." (PMID 30399192, 2018). "It has been observed that the expressions of fractalkine and its receptor CX3CR1 are upregulated in atherosclerosis lesions, and the severity of atherosclerosis is greatly improved by inhibiting their expressions, indicating that the fractalkine/CX3CR1 pair is closely related to atherosclerosis." (PMID 24307998, 2013). "A decline in CX3CR1 expression in macrophages at the site of lesions may be beneficial, eg suppressing the recruitment and retention of macrophages in blood vessel walls and thereby retarding the development and progression of atherosclerosis." (PMID 22815945, 2012). "This association seems to be influenced by the presence of IR, which induces a worse metabolic profile, aggravates atherosclerosis, and upregulates the CX3CL1/CX3CR1 axis." (PMID 41153665, 2025). "What points to a crucial signalling pathway in vascular diseases such as atherosclerosis, COVID-19-related vascular complications, and CMV-induced endothelial toxicity is the breadth of studies linking CX3CR1 with these conditions." (PMID 37510939, 2023). "Previous studies have shown that CCL2 inhibition alone or in combination with CX3CR1 and CCR5 leads to decreased monocyte recruitment and thus inhibits atherosclerosis occurrence." (PMID 35509837, 2022). "The use of the Reversa mouse model, which is a model that is widely used to study atherosclerosis regression, also pointed to the crucial role of CXCR2 and CX3CR1 in lesion regression." (PMID 34501271, 2021). "Monocyte subsets also differentially express the C-C chemokine receptor type 2 (CCR2) and the CX3C chemokine receptor 1 (CX3CR1), each of which are chemokine receptors with prominent functions in cell migration and endothelial adhesion during atherosclerosis." (PMID 34439835, 2021). "In this sense, elevated circulating nLDL levels are associated with an increment in the percentage of CMs that can migrate into endothelial tissue by mainly expressing CX3CR1 and CCR2 in ApoE−/− mice, an animal model of atherosclerosis." (PMID 34439835, 2021). "Many of the expanded CD8 T cells express high levels of the vascular-endothelium homing chemokine receptor CX3CR1, and plasma levels of its ligand–fractalkine (CX3CL1)–are upregulated in HIV infection and in atherosclerosis." (PMID 32976527, 2020). "DNA vaccination against CX3CR1 (DEC205-CX3CR1) decreased macrophage recruitment and significant protection from atherosclerosis." (PMID 32686027, 2020).
atherosclerosis (continued). "CX3C chemokine receptor 1 (CX3CR1) has been identified as an important adhesion molecule in migration, adhesion and recruitment of monocytes during the pathogenesis of atherosclerosis CX3CR1 was validated as one of the direct target genes of miR-296-3p." (PMID 30134788, 2018). "The knockout and transgenic studies provide convincing proof that individual chemokine-chemokine receptor signalling pathways are important in atherosclerosis, particularly the CCL2/CCR2, CCL5/CCR5 and CX3CL1/CX3CR1 pathways." (PMID 28282403, 2017). "The present study demonstrates an increased CX3CR1 expression in FH subjects, particularly in FH ATX+ subjects, supporting a possible involvement of monocyte CX3CR1 in subclinical atherosclerosis during pathological conditions such as hypercholesterolemia." (PMID 25875611, 2015). "Evidence from CX3CL1-/-, CX3CR1-/-, and CX3CR1 pharmacologic inhibition studies in mice with a background of hypercholesterolemia mechanistically tied CX3CL1 to atherosclerosis." (PMID 24995121, 2014). "Administration of NaHS at either the early or the advanced stage of atherosclerosis suppressed the aortic expression of CX3CL1 and CX3CR1, together with reduced plaque size and IMT thickness in the main branches of the aortic arch." (PMID 22815945, 2012). "To further demonstrate the involvement of H2S in regulating CX3CL1 and CX3CR1 expression during atherosclerosis and to establish its pathophysiological relevance in vivo, we examined the effect of H2S on CX3CL1 and CX3CR1 expression in fat-fed apoE−/− mice." (PMID 22815945, 2012). "The nuclear receptor PPAR-γ has the inherent capacity to regulate expression of macrophage chemokine receptors (CX3CR1 and CCR2) in lipid-mediated inflammation in atherosclerosis lesions." (PMID 22815945, 2012). "Thus, despite several pathophysiological similarities and risk factors between atherosclerosis and PE, we did not confirm our hypothesis of a protective effect of genetic CX3CR1 polymorphisms in PE." (PMID 19587779, 2009). "CX3CL1 expression by dysfunctional endothelium may attract CX3CR1+CD8+ T cells, influencing atherosclerosis progression in both PLWH and PWoH." (PMID 39000373, 2024). "E.g., it has been shown in atherosclerosis that the expression and function of chemokine receptors such as Ccr2, Ccr5 and Cx3cr1 differs between classical and non-classical monocytes." (PMID 36741412, 2022). "Il15 has been detected in atherosclerosis plaques as a proinflammatory cytokine and could attenuate SMC proliferation possibly via inhibiting the chemokine receptor CX3CR1." (PMID 34545275, 2021). "In this report, we define a novel model of CD8 T cell involvement in atherosclerosis whereby CX3CL1 and IL-15 operate in tandem within the vascular endothelium to promote infiltration by activated CX3CR1+ memory CD8 T cells that drive further endothelial activation via TNF." (PMID 32976527, 2020). "In atherosclerosis and murine lupus nephritis models, Ly6Clo monocytes were recruited to lesions independent of CX3CR1." (PMID 31888754, 2019). "However, miR-296-3p has the potential to inhibit atherosclerosis by regulating adhesion molecules, including ICAM-1 and CX3CR1." (PMID 30134788, 2018). "Both CX3CL1 levels, and CD3+CD8+ CX3CR1+ T cell levels increase in patients with chronic coronary artery disease and acute coronary syndromes with plaque rupture, strongly supporting a link between CX3CL1 and atherosclerosis in humans." (PMID 24995121, 2014). "In addition, during atherosclerosis, recruitment of monocytes to atherosclerotic plaque relies on CCR2, CX3CL1/CX3CR1 and CCR5, showing that multiple receptors can be used to recruit these cells to inflammation sites." (PMID 23554169, 2013). "In mouse models of atherosclerosis, absence of FKN or its receptor CX3CR1 protects from atherosclerotic lesion formation and humans with a polymorphism for CX3CR1 exhibit a decreased risk for developing coronary artery disease." (PMID 22916279, 2012).